DZIP1L (DAZ interacting zinc finger protein 1 like)
Description:
Involved in primary cilium formation. Probably acts as a transition zone protein required for localization of PKD1/PC1 and PKD2/PC2 to the ciliary membrane.
Synonyms: FLJ32844; DZIP2; PKD5
Tractability: PROTAC: ubiquitination databases record sites on it.
Gene: Protein-coding gene on chromosome 3 (138,061,987 to 138,115,839, reverse strand). Ensembl gene ENSG00000158163.
Subcellular location: Cytoplasm, cytoskeleton, cilium basal body; Cytoplasm, cytoskeleton, microtubule organizing center, centrosome, centriole
Subcellular location (Human Protein Atlas): Basal body; Cytokinetic bridge; Microtubules; Mitotic spindle; Primary cilium; Cytosol; Nucleoplasm
Gene Ontology:
Molecular function: protein binding
Biological process: cilium assembly; regulation of protein localization
Cellular component: centriole; ciliary basal body; cytoplasm
Genetic constraint (gnomAD): Loss-of-function variants: 84 observed, 80.12 expected, observed/expected ratio (o/e) 1.05, 90% interval 0.88 to 1.26. The upper end of that interval is the gene's LOEUF score, 1.26, which puts it in group 5 of 6, group 1 being the genes least tolerant of losing a copy. Missense variants: 867 observed, 901.34 expected, observed/expected ratio (o/e) 0.96, 90% interval 0.91 to 1.02. Synonymous variants: 339 observed, 349.83 expected, observed/expected ratio (o/e) 0.97, 90% interval 0.89 to 1.06.
Gene-disease validity (ClinGen):
ClinGen rates the evidence that DZIP1L causes each of these diseases.
autosomal recessive polycystic kidney disease (autosomal recessive): Definitive. An inherited disorder characterized by the development of cysts affecting the collecting ducts.
Homologues: Orthologues: chimpanzee DZIP1L (99% identical), macaque DZIP1L (89% identical), guinea pig DZIP1L (79% identical), rabbit DZIP1L (78% identical), mouse Dzip1l (77% identical), rat Dzip1l (77% identical), pig DZIP1L (55% identical), dog DZIP1L (38% identical), tropical clawed frog dzip1l (31% identical), zebrafish dzip1l (28% identical), Drosophila melanogaster Rilpl (8% identical), Caenorhabditis elegans rilp-1 (7% identical). Paralogues in human: DZIP1 (30% identical), RILPL1 (10% identical), RILP (8% identical), RILPL2 (5% identical).
Diseases named in the same sentence as DZIP1L in open-access papers:
DZIP1L is named in the same sentence as 24 diseases in open-access papers, as found by Europe PMC text mining. Sharing a sentence is not in itself a finding about the gene and the disease. The quoted sentences say what the papers report.
autosomal recessive polycystic kidney disease (9 papers, 2018 to 2025). "DZIP1L encodes a protein found in the transition zone of cilia, and mutations have been associated with autosomal recessive polycystic kidney disease, as well as craniofacial deformities and polydactyly." (PMID 37884875, 2023). "A recent study identified SEPT2 as an interaction partner of DAZ interacting protein 1‐like (DZIP1L), encoded by DZIP1L, which is mutated in autosomal recessive polycystic kidney disease." (PMID 30004646, 2019). "As a genetic cause of human autosomal recessive polycystic kidney disease (ARPKD), DZIP1L is implicated in the ciliary entry of PKD proteins, yet the underlying mechanism remains elusive." (PMID 38634253, 2024). "DZIP1L, identified as one of the genetic causes of human autosomal recessive polycystic kidney disease (ARPKD), is an evolutionarily conserved ciliary basal body protein." (PMID 38634253, 2024). "Autosomal recessive polycystic kidney disease (ARPKD) is mainly a result of the biallelic pathogenic variants in the PKHD1 (PKD type 4) and DZIP1L (PKD type 5) genes, besides numerous syndromic PKD genes." (PMID 34032358, 2021). "In addition to PKHD1 (polycystic kidney and hepatic disease 1), mutations in DZIP1L (DAZ interacting zinc finger protein 1 like) have recently been associated with ARPKD." (PMID 30003073, 2018). "Autosomal recessive polycystic kidney disease (ARPKD) is a rare and severe renal cystic disease caused by homozygous or compound heterozygous variants of polycystic kidney and hepatic disease 1 (PKHD1) or DAZ interacting zinc finger protein 1 like (DZIP1L)." (PMID 34977057, 2021).
cystic kidney disease (8 papers, 2019 to 2025). A congenital or acquired kidney disorder characterized by the presence of renal cysts. "The pathological significance of DZIP1L aberrations was confirmed using mice with chemically induced Dzip1l mutations which caused cystic kidney disease." (PMID 32276433, 2020). "While DZIP1L-related polycystic kidney disease certainly represents a rare form of the disease, our results emphasize the importance of including DZIP1L in multigene panels and in the data analysis of whole-exome sequencing for cystic kidney diseases." (PMID 35211789, 2022). "None of the unsolved patients had have family history of kidney disease, therefore mutations in autosomal recessive genes that lead to ARPKD-like phenotypes such as the DZIP1L or even in dominant cystic kidney disease genes such as HNF1B, PKD1 and PKD2 that often occur de novo are possible." (PMID 32799815, 2020). "A cystic kidney disease panel should include adequate coverage of PKD1, PKD2, PKHD1, Daz-interacting zinc-finger protein 1-like (DZIP1L), HNF1B and genes for other ciliopathies such as nephronophthisis (NPHP) and Bardet–Biedl syndrome (BBS)." (PMID 31118499, 2019). "Mutations in other ciliopathic genes which were not in our NGS ciliopathy panel (e.g. DZIP1L, CEP83, or many other genes that are gradually described in literature as causing ciliopathies) could cause the phenotype of cystic kidney disease in unresolved patients." (PMID 32574212, 2020).
ciliopathies (6 papers, 2019 to 2025). "Hence, the findings illuminate an evolutionarily conserved role of DZIP1L in TFs architecture and function, highlighting TFs as a vital part of the ciliary gate implicated in ciliopathies ARPKD." (PMID 38634253, 2024). "This study unveils an evolutionarily conserved role of DZIP1L in modulating the architecture and function of ciliary transition fibers (TFs), highlighting TFs as a vital part of the selective ciliary gate implicated in ciliopathies ARPKD." (PMID 38634253, 2024). "Our results thus not only reveal DZIP1L as a key player in regulating the poorly understood cilia trafficking of polycystins, but also underscore the physiological significance of a functional cilia gate in the context of ciliopathies beyond PKDs." (PMID 38634253, 2024).
polycystic kidney disease (6 papers, 2017 to 2023). A usually autosomal dominant and less frequently autosomal recessive genetic disorder characterized by the presence of numerous cysts in the kidneys leading to end-stage renal failure. "In the present study, we detected two different, novel DZIP1L mutations in homozygous form in four patients with polycystic kidney disease from three consanguineous families." (PMID 35211789, 2022). "We performed next-generation sequencing (NGS) in three consanguineous families comprising four children, all presenting with polycystic kidney disease, and thereby identified two different, not previously reported, homozygous DZIP1L sequence variants." (PMID 35211789, 2022). "Overall, DZIP1L-related ARPKD is a rare form of polycystic kidney disease." (PMID 35211789, 2022). "For genetic workup, further polycystic kidney disease genes were analyzed, PKD1 and PKD2 in 12, HNF1B in 8, and DZIP1L and GANAB in 5 children each without detection of variants." (PMID 35812281, 2022).
autosomal dominant polycystic kidney disease (1 paper, 2022). Autosomal dominant form of polycystic kidney disease. "DZIP1L is located at the basal body of the primary cilium, and impaired function of DZIP1L is associated with a defect in the ciliary trafficking of the two major proteins for autosomal dominant polycystic kidney disease (ADPKD), polycystin-1 and polycystin-2." (PMID 35211789, 2022).
colorectal cancer (1 paper, 2016). A primary or metastatic malignant neoplasm that affects the colon or rectum. "The human Iguana gene DZIP1L has been suggested to be part of the Hedgehog signaling pathway, which is often activated in gastric cancer but not often in colorectal cancer." (PMID 26872740, 2016).
cancer (1 paper, 2015). A tumor composed of atypical neoplastic, often pleomorphic cells that invade other tissues. "Six of fifty genes were not previously known to associate with cancer (HMGB1L5, LRRC58, GPR149, DZIP1L, C3orf77, and NUDT16)." (PMID 26491211, 2015).
DZIP1L also shares sentences with these, for which no sentence is quoted: Hypertension (2 papers); nephronophthisis (2); breast carcinoma (1); congenital anomalies of the kidney and urinary tract (1); Failure to thrive (1); gastric cancer (1); glioma (1); Hepatosplenomegaly (1); infection (1); Infertility (1); kidney (1); kidney disease (1); medullary cystic kidney diseases (1); nephronophthisis 1 (1); polycystic liver disease 1 (1); renal agenesis (1); renal hypoplasia (1).